SMAD3 (SMAD family member 3)
Diseases named in the same sentence as SMAD3 in open-access papers (continued):
Sharing a sentence is not in itself a finding about the gene and the disease.
breast carcinoma (continued). "Based on these results it appears inactivating SMAD3 and SMAD4 germline mutations and splicing defects appear to occur very infrequently in breast cancer." (PMID 21835029, 2011). "For the qPCR analysis, cDNA harboring SMAD3 and SMAD4 variants were categorized as breast cancer cases with variants (BC-VAR) and controls with variants (CO-VAR)." (PMID 21835029, 2011). "Future research to explore the mechanisms of deregulation of SMAD3 and SMAD4 expressions will be essential in determining their association with breast cancer risk and tumorigenesis." (PMID 21835029, 2011). "A complex of Smad3/4 mediates TGF-β inhibition of ERα-mediated estrogenic activity of gene transcription in breast cancer cells, and Smad4 is essential and sufficient for such repression." (PMID 19943940, 2009). "Either overexpression of Smad3 or inhibition of Smad4 expression switches TGF-β to an activator for ERα transactivation in breast cancer cells." (PMID 19943940, 2009). "MCF-7 breast cancer cells were co-transfected with expression plasmids of Smad2, Smad3, Smad4, or Smad4 in combination with either Smad2 or Smad3." (PMID 19943940, 2009). "Taken together, these results show that loss of BRCA1 or reduced BRCA1 expression significantly modulated TGF-β induced activation of Smad3 and Smad4 in breast cancer cells." (PMID 19768112, 2009). "The MCF-7 hormone-dependent breast cancer cell line was transiently transfected with Smad2/4 or Smad3/4 and treated with TGF-β1 for 8 hours." (PMID 19943940, 2009). "In contrast, the tumour suppressor Smad pathway has been shown to mediate the prometastatic function of TGF-β in the development of breast cancer bone metastasis, and dominant negative Smad3 inhibits lung metastasis of breast cancer cells in animal models." (PMID 18781153, 2008). "In breast cancer, lactate modulates cancer cell invasion via the TGFβ1/Smad3/MMP2/9 signaling axis." (PMID 40646747, 2025). "Moreover, according to our results, SMAD3 and SMAD7 are predicted targets of miR‐195‐5p, and their altered expression is associated with epithelial‐to‐mesenchymal transition (EMT) in breast carcinoma, as reported in previous studies." (PMID 40548926, 2025). "Additionally, ginkgetin-mediated inhibition of the miR-122-5p/GALNT10/Smad3 signaling axis significantly attenuated the migratory capacity of breast cancer MDA-MB-231 cells." (PMID 40762894, 2025). "Similarly, Smad3 knockout in breast cancer models blocks TGFβ1-induced MMP9 expression, inhibiting metastasis." (PMID 40646747, 2025). "SMAD3 gene expression was not related to tumor mutation load in patients with breast cancer, which also verifies the results of gene mutation distribution map analysis." (PMID 38514720, 2024). "However, in our study, SMAD3 knockdown suppressed breast cancer growth, which demonstrated that SMAD3 knockdown can inhibit tumor immune escape in vivo." (PMID 38514720, 2024). "Our study showed overexpression of SMAD3 in all five types of breast cancer, which may be related to a significant reduction in miR-145 activity." (PMID 39337574, 2024). "In conclusion, we identified a novel prometastasis TGF‐β/Smad3 cofactor in breast cancer." (PMID 39225541, 2024). "TGF-β/SMAD was shown to be regulated by the interaction of SMAD3 with IKKα in breast cancer cells." (PMID 38994944, 2024). "To investigate whether SMAD3 knockdown can synergistically affect the tolerance of breast cancer cells to BAY-1161909 or XK-469, we first investigated the inhibitory effects of individual drugs." (PMID 38514720, 2024). "In addition, OSR1 acts directly on SMAD2/3 and phosphorylates 223Thr in the SMAD2-linked region and 179Thr in the SMAD3-linked region, promoting TGF-β pathway signalling and breast cancer metastasis." (PMID 37685308, 2023). "Importantly, SUMO-SnoN suppressed the ability of overexpressed Smad2 and Smad3 to promote EMT in breast carcinoma organoids." (PMID 37414747, 2023).
breast carcinoma (continued). "Additionally, HCC1359 breast cancer cells lack phosphorylation levels of SMAD3, which correlate with decreased TMEPA1 expression." (PMID 37987362, 2023). "In HER2+ breast cancer, overexpression of Cyclin E causes increased non-classical phosphorylation of SMAD Family Member 3 (SMAD3), conferring trastuzumab resistance." (PMID 36998461, 2023). "In addition, CPTAC data showed a significantly positive correlation between the protein expression levels of YTHDC1 and SMAD3 in breast cancer patient samples, which supports regulation of SMAD3 by YTHDC1." (PMID 35966596, 2022). "Zhu and colleagues used the CAGA12-luciferase reporter in breast cancer cells to study TGF-β/SMAD3 activity by measuring luminescence during tumorigenesis in vivo, whereas others created a transgenic CAGA12-luciferase mouse, studying TGF-β/SMAD3 response to injury." (PMID 35626109, 2022). "Finally, we applied our model to disambiguate the roles of Smad2 and Smad3 in breast cancer disease progression from a publicly available dataset." (PMID 35858839, 2022). "Furthermore, treatment with the TβRII agonist TGF‐β1 rescued the reduced expression of TβRII and p‐Smad3 as well as the migration ability of breast cancer cells mediated by HTR1A overexpression." (PMID 35199941, 2022). "Moreover, IGFBP-3 has been shown to bind to and activate TGF-β receptor, thus leading to phosphorylation of Smad2 and Smad3 in breast cancer cells." (PMID 35798794, 2022). "Additionally, in vitro studies have demonstrated that CCL2/CCR2 mediated p42/44MAPK and SMAD3 pathways in breast cancer cells are important in growth, survival, migration and invasion." (PMID 33888841, 2021). "Moreover, tRF-17 attenuated the THBS1-mediated TGF-β1/Smad3 signaling pathway in breast cancer cells." (PMID 33912465, 2021). "Moreover, TGF-β1 supplement significantly restored Erk1/2 and SMAD3 phosphorylation levels individually or simultaneously which is inhibited by LAE supplement in three subtypes of breast cancer cells." (PMID 33602253, 2021). "Taken together, these data demonstrate that KAT6A‐induced acetylation of SMAD3 promoted metastasis not only by enhancing breast cancer stem‐like cell properties but also by inducing the MDSCs recruitment by persistent production of immune response‐related cytokines." (PMID 34392614, 2021). "Furthermore, SMAD3 cooperation with p42/44MAPK was found to be important in CCL2/CCR2 mediated breast cancer cell survival and motility." (PMID 33888841, 2021). "First, the stabilized Smad3 by PSG9 could regulate breast cancer cell proliferation and tumor growth." (PMID 33377651, 2020). "Interestingly, TrkB directly associates with SMAD2, SMAD3, and SMAD4 in breast cancer tissues and cancer cell lines." (PMID 32340410, 2020). "Furthermore, knockdown of SMAD3 produced a consistent phenotype of miR-135-5p overexpression in breast cancer cells." (PMID 33033523, 2020). "However, OLA1 and TGF β 1, SMAD3 SMAD4 has a strong positive correlation in the breast cancer tissue of the TCGA database (right)." (PMID 32528278, 2020). "Distinct effects of SMAD2 and SMAD3 were reported in breast cancer bone metastasis, pancreatic ductal adenocarcinoma cell proliferation and migration, HaCaT keratinocyte cell growth, TGF-β autoinduction in clostridium butyricum-activated dendritic cells and TGF-β induced transcription." (PMID 32746934, 2020). "Consistent with this, SMAD3, which plays an essential role in TGFβ signalling, has been shown to link shape information to transcription in breast cancer cells, while WNT signalling can be linked to cell microenvironment via the differential localisation of its downstream effector β‐catenin." (PMID 32141232, 2020). "We showed that blocking the function of TMEPAI in MDA-MB-231 breast cancer cells strongly suppressed the formation of metastatic foci in lungs of mice, thus supporting our Smad3-TMEPAI-PTEN axis hypothesis in triple negative breast cancer progression." (PMID 31798766, 2019).
breast carcinoma (continued). "TGF-β induces Gli1 and Gli2 in a Smad3-dependent manner in epithelial and mesenchymal cell lines, dermal fibroblasts, osteolytic Langerhans cells, breast carcinoma cells, and pancreatic ductal adenocarcinoma cells." (PMID 31297044, 2019). "Based on the results published, we hypothesized that aberrant functional expression of Smad2 and Smad3 in breast cancer contributes to the pro-oncogenic activities of TGF-β." (PMID 31798766, 2019). "Systemic administration of BMP7 in breast cancer mouse models has proven to significantly inhibit bone metastases originating from human prostate and breast cancer, by reducing TGFβ-dependent SMAD3/4 activation, activating nuclear signaling of SMAD1/4/5, and restoring E-cadherin levels." (PMID 31547567, 2019). "Although earlier inferences regarding the dual role of TGF-β in carcinogenesis have been obtained using different in vitro and in vivo models, a comparative analysis of Smad2 and Smad3 proteins allowed us to determine how such a functional switch truly occurs in breast cancer." (PMID 31798766, 2019). "While the inactivating mutations in Smad2 and Smad3 have not been reported in breast cancer, this has been reported in Smad4." (PMID 31798766, 2019). "Thus, we show that BMP7 inhibits telomere maintenance by a mechanism involving BMPRII receptor and Smad3 signaling to suppress hTERT gene expression in breast cancer cells." (PMID 27696331, 2017). "In conclusion, we demonstrate that BMP7 exerts a potent inhibitory effect on telomerase activity and telomere maintenance in human breast cancer cells, causing cancer cell ageing and death, via BMPRII receptor and Smad3 signaling to repression of the hTERT gene." (PMID 27696331, 2017). "To examine the involvement of telomerase inhibition in breast cancer cell apoptosis, we observed an increased response of apoptosis to the transient overexpression of Smad3 that is an hTERT gene repressor or to the transient expression of the hTERT shRNA to silence the hTERT gene." (PMID 27696331, 2017). "Thus, BMP7 employed Smad3 to repress the hTERT gene, inhibit telomerase activity and induce telomere shortening in cultured breast cancer cells." (PMID 27696331, 2017). "In addition to stimulating Smad1, Smad5 and Smad8 phosphorylation and nuclear translocation, BMP7 also induces Smad3 phosphorylation and nuclear accumulation in breast cancer cells and silencing Smad3 abrogates BMP7-induced telomerase inhibition." (PMID 27696331, 2017). "Recently, contribution of SMAD3 to G1 arrest was reported in breast cancer." (PMID 27054113, 2016). "Smad3 expression levels are low in breast cancer stem cells from human patients." (PMID 27588495, 2016). "Our findings contribute novel data showing that RAB1B may serve as a novel and important biomarker to stratify patients with advanced breast cancer for more effective treatments with specific targeted therapies aimed at the TGF-β-SMAD3 pathway." (PMID 25970785, 2015). "We found that high expression of our TGF-β/Smad3 tumor-suppressor signature was associated with good outcome only in patients with ER+ tumors, suggesting that TGF-β plays a particularly important role in limiting progression of this breast cancer subtype." (PMID 24890385, 2014). "Our integrated genomic strategy allowed us to dissect out a core TGF-β/Smad3 gene signature that specifically reflected the tumor-suppressive activities of TGF-β in vivo and was associated with good outcome in multiple independent ER+ breast cancer cohorts." (PMID 24890385, 2014). "Thus the tumor-suppressive effects of TGF-β in ER+ breast cancer include a role in enhancing cellular differentiation, and Smad3 is a critical mediator of this activity." (PMID 24890385, 2014).
breast carcinoma (continued). "Our data suggest that TGF-β/Smad3-mediated tumor-suppression plays an important role in the natural history of ER+ breast cancer, and that tumor-suppressive effects of TGF-β are still evident in the tumor at the time of surgery and influencing disease outcome for a significant fraction of patients." (PMID 24890385, 2014). "In addition, Smad3 has been shown to be an important contributor to breast cancer cell invasion by controlling the expression of MMP-2 and MMP-9, two metalloproteinases involved in matrix degradation and invadopodia functions." (PMID 23405166, 2013). "Together these data suggest that in breast cancer Smad3 pro-invasive functions are mediated by p21 and that targeting p21 may prove useful to improve the clinical course of metastatic patients." (PMID 22995475, 2012). "In this paper, we have analyzed the role that thermodynamic fluctuations in energy at the cell-level play in the synthesis of transcription factors MNDA, POU2AF1, MEF2C and SMAD3 and how can this energetic constrains be related with the presence of primary breast carcinomas." (PMID 22952604, 2012). "Indeed, we previously reported that Six1 and nuclear localization of the TGF-β effector Smad3 were significantly correlated in human breast cancer samples." (PMID 22765220, 2012). "As it has been suggested that SMAD3 and SMAD4 mutations are rare in breast cancer, we quantitatively assess whether this is the case in the germline." (PMID 21835029, 2011). "Interpreting how changes in expression of SMAD3 and SMAD4 affect their activities in the cell may distinguish their roles as a tumor suppressor or oncogene in breast cancer susceptibility." (PMID 21835029, 2011). "TGF-β-Smad3 signaling acts as critical role in breast cancer cell invasion and EMT." (PMID 20520770, 2010). "In breast carcinoma cells that lack one component of the Smad3/4 complex, Smad3 or Smad4 may act as a coactivator or corepressor for ERα that confers a TGF-β activating or suppressing signal on the estrogen signaling pathway." (PMID 19943940, 2009). "Similarly, the focal adhesion adaptor p130Cas (Crk-associated substrate, 130 kDa), which is overexpressed in breast cancer cells, promotes TGF-β1-induced EMT by binding to Smad3/TβRI, promoting the degradation of Smad3 and thereby suppressing the cytostatic activities of Smad3." (PMID 38675493, 2024). "In the last step, miRNA microarray analysis was performed to identify differentially expressed miRNAs in each breast cancer subtype, and then it was determined whether they could participate in the regulation of the expression of SMAD3, SMAD4, SMAD5, and SMAD7 selected in previous steps." (PMID 39337574, 2024). "Therefore, ZNF8 is a new Smad3 cofactor that involved in multiple steps of breast cancer lung metastasis, and targeting ZNF8 may be a potential strategy for preventing breast cancer lung metastasis." (PMID 39225541, 2024). "Collectively, our data underscore the importance of EZH2-mediated SMAD3 K53/K333 methylation in metastasis and indicate that SMAD3 methylation might function as an important factor in predicting overall survival of patients with breast cancer." (PMID 35085106, 2022). "In addition, we asked whether the expression of the SMAD3 gene signature was correlated with tumor progression, as defined by metastasis-free survival in breast cancer and progression-free survival in lung adenocarcinoma." (PMID 35681731, 2022). "Because the TGF-β/SMAD3 signaling can upregulate CXCR4 expression in breast cancer, promoting metastasis, and its ligand CXCL12 is enriched in the bone marrow microenvironment, we evaluated whether SOST silencing could change in the expression of these factors in SCP2 cells." (PMID 36581888, 2022).
breast carcinoma (continued). "Therefore, we hypothesized that tRF-17-79MP9PP might contribute to breast cancer progression via the THBS1/TGF-β1/Smad3 pathway." (PMID 33912465, 2021). "Therefore, we hypothesized that tRF-17-79MP9PP-mediated THBS1 inhibition may lead to the inactivation of TGF-β1/Smad3 signaling pathway in breast cancer cells." (PMID 33912465, 2021). "To further confirm the KAT6A acetylation of SMAD3, we generated two rabbit polyclonal antibodies that specifically recognized SMAD3‐K20ac or SMAD3‐K117ac through a commercial vendor and validated their specificity in a clinical breast cancer specimen and MDA‐MB‐231 cells." (PMID 34392614, 2021). "Moreover, quantitative analysis demonstrated that the double knockdown of Sp1 and Smad3 triggered an additive effect on EGFR expression in breast cancer cells but did not cause a synergistic effect." (PMID 29215776, 2018). "Smad2 knockdown increases the aggressiveness of metastatic human breast cancer MDA-MB-231 cells while Smad3 knockdown prolongs the latency and delays the growth of bone metastasis, indicating that selective targeting of Smad2 or Smad3 may result in different therapeutic responses." (PMID 27641158, 2016). "We speculate that Smad3 is more crucial than Smad2/4 for the G3BP1-induced EMT in breast cancer." (PMID 25962958, 2015). "Thus, to determine whether miR-191:TGFβ2 induced breast cancer migration is SMAD3 dependent, we silenced SMAD3 by using SMAD3-specific siRNA and analyzed the effect on miR-191 induced breast cancer migration." (PMID 25867965, 2015). "The downstream molecular events of BMP-3B silencing in lung cancer progression are still not clear and might include phosphorylation of Smad proteins as recently reported that BMP-3B inhibits tumor formation of mammary tumor cells by promoting phosphorylation of Smad3." (PMID 22537242, 2012). "Given that the SMAD3 mutations are infrequent and that its expression is elevated in peripheral blood and tumor tissues, SMAD3 does not seem to be inactivated and is unlikely to contribute as a tumor suppressor during breast cancer development." (PMID 21835029, 2011). "However, it has been difficult to ascertain whether SMAD3 and SMAD4 mutations in breast cancer are truly rare or this understanding is due to the comparatively small sample sizes screened as noted from COSMIC." (PMID 21835029, 2011). "Thus, it is currently unknown whether germline SMAD3 and SMAD4 mutations are involved in breast cancer predisposition." (PMID 21835029, 2011). "It has been reported that aberrant SMAD3 and FOXO1 signaling is involved in trastuzumab resistance in breast cancer cells." (PMID 40925917, 2025). "In breast cancer, silencing KIF4A diminishes Smad3 phosphorylation, alters TGF-β1/Smad3 pathway activity, and influences epithelial-mesenchymal transition (EMT) as well as immune factor expression." (PMID 41361459, 2025). "Smad3 interacts with BRCA1 in response to TGF-β stimulation and inhibits BRCA1-dependent DNA repair in MCF7 breast cancer cells (luminal type) by disrupting BRCA1 nuclear complexes." (PMID 38569937, 2024). "SMAD4, SMAD2, SMAD3, SMAD7, SMAD1, SMAD6, and SMAD5 showed genetic variation in 1.8%, 1.2%, 1.1%, 0.8%, 0.7%, 0.6%, and 0.5% of patients with breast cancer, respectively." (PMID 38514720, 2024). "shRNA knockdown of BCL3 in breast cancer cells with concomitant TGF-β stimulation, revealed decreased SMAD3 phosphorylation, decreased SMAD3 protein levels and attenuated TGF-β reporter luciferase assay activity." (PMID 38195591, 2024). "Breast cancer lung metastasis is a complex process and has a poor prognosis, in which TGF‐β/Smad3 pathway plays a crucial role." (PMID 39225541, 2024). "The interaction between ZNF8 and Smad3 was confirmed in MDA‐MB‐231, MCF‐7, and T47D breast cancer cells by co‐immunoprecipitation (Co‐IP), which also showed that the interaction was enhanced after TGF‐β pathway activation." (PMID 39225541, 2024).